CD4 (CD4 molecule)
Diseases named in the same sentence as CD4 in open-access papers (continued):
Sharing a sentence is not in itself a finding about the gene and the disease.
tuberculosis (continued). "This view is supported by a recent study showing that P2RX7 expression in CD4+ T cells is particularly important for cell migration, proliferation and production of IFNγ in the pulmonary parenchyma during severe tuberculosis and influenza." (PMID 36993971, 2023). "In human studies, CD4+ M.tb-specific IL-17- and IL-22-producing cells have been detected in individuals exposed to tuberculosis, although only IL-22 is seen in the lung." (PMID 37415827, 2023). "This evidence supports previous findings that opportunistic infections, including tuberculosis, are more common in patients with low CD4 levels (under 200 cells/μl), bedridden/ambulatory patients, and those in advanced WHO clinical stages." (PMID 37723415, 2023). "Several studies have demonstrated a decrease in the percentage and absolute value of CD4+ cells in the peripheral blood of children and adults with active tuberculosis, which indicates their increased pool in the focus of infection." (PMID 37686061, 2023). "For example, CD69 is a co-stimulatory receptor and a marker of early T-cell activation, and elevated levels of CD4+, CD69+, IFN-γ+ T cells are associated with early active or recent tuberculosis." (PMID 37686061, 2023). "For further analysis, all patients were redistributed into groups according to the CD4+ cell count at the onset of tuberculosis development." (PMID 37606452, 2023). "Male individuals between the ages of 31 and 40 were more affected by both HIV and tuberculosis, and in most of these cases, their CD4 cell count was below 200 cells/μl." (PMID 37667708, 2023). "CD8+ T and NK cells are essential components of the immune response to tuberculosis, with critical roles played by macrophages, effector CD4+ T lymphocytes, and IFN-γ, produced by Th1 cells and triggers macrophage activation." (PMID 37950733, 2023). "The distribution of sex, age, occupation, education, CD4 cell count, tuberculosis status, and hypertension status was similar for patients with (n = 1975; 93%) or without (n = 154; 7%) a follow-up BMI measurement." (PMID 37607169, 2023). "The expression of PD-1 on CD4 and CD8 T cells does rise after prolonged exposure to tuberculosis antigens, and inhibiting PD-1 or PD-L1 using an antibody boosts CD4 and CD8 T-cell activity." (PMID 36674038, 2023). "WHO 2021 recommends screening for tuberculosis with urine lipoarabinomannan (LAM) for inpatients (CD4 + < 200 cells/mm3) or outpatients (CD4 + < 100 cells/mm3), any CD4 count with symptoms, or if seriously ill." (PMID 37996881, 2023). "Antiretroviral therapy (ART) was initiated after age five years in 56%, 43% had prior pneumonia or tuberculosis, 11% had low CD4 count and 79% were virologically suppressed." (PMID 37556423, 2023). "The results of this study showed that the ATBI have impaired immune function, and mainly have reduced CD4+ T cells, which consistent with the anti-tuberculosis immunological response effect." (PMID 37103584, 2023). "The role of HIF1a in tuberculosis is ambiguous: it promotes antimicrobial activity of human macrophages against M.tb, but also impairs CD4 T cell activation and differentiation, leading to increased susceptibility to M.tb infection." (PMID 37834286, 2023). "The current study was targeted on identifying the common determinants of tuberculosis and CD4 cell count of patients." (PMID 38974259, 2023). "These were in participants with CD4 cell counts <100 cells/mm3 (aRD -7.1%, -13.7% to -0.4%), participants with haemoglobin < 8g/dL (aRD –9.0%, –16.6% to –1.3%), and participants with tuberculosis in differential diagnosis (aRD –5.7% –10.9% to –0.5%)." (PMID 36963024, 2023). "These patients are at high risk of death mainly due to Tuberculosis and cryptococcal meningitis, even after starting ART (which can increase the inflammatory response) and the risk increases with decreasing CD4 cell count." (PMID 37608300, 2023).
tuberculosis (continued). "After adjustment for tuberculosis status, the rs4986790-G (TLR4) and rs5743551-G (TLR1) alleles were significantly associated with the changes in CD4+ cell count above/below 200 cells/mm3." (PMID 37606452, 2023). "Protective immunity against tuberculosis is largely due to a cellular immune response, in which antigen-specific functional CD4+ T cells and Th1/Th17 cytokines are essential for the protection against MTB." (PMID 36860878, 2023). "Age group, sex, marital status, BMI categories, co-morbidities (diabetes mellitus, renal disease, and tuberculosis), and CD4 counts were variables included in the model using backward elimination method." (PMID 37908015, 2023). "As a result, B-cells contribute to the induction of CD4+ T-cells responses to tuberculosis, providing early protection against infection and driving antibody-mediated phagocytosis in which they modify macrophage behavior." (PMID 37415827, 2023). "Tuberculosis is one such opportunistic infection that affects HIV-infected individuals, and the level of CD4+ cell count can be considered as a risk factor for the development of tuberculosis in this population." (PMID 37606452, 2023). "In this meta-analysis study, CD4 counts of less than 200 cells/μl, advanced WHO clinical stages (3/4), and being bedridden/ambulatory were risk factors for tuberculosis in HIV patients." (PMID 37723415, 2023). "WHO Stage III/IV and tuberculosis symptoms were associated with delays in ART initiation; clinic size and having a CD4 count done were associated with an increased likelihood of SDI." (PMID 37153118, 2023). "In this high-risk region, the use of isoniazid preventive therapy (IPT), co-trimoxazole prophylaxis, and antiretroviral therapy should be scaled up continuously to reduce opportunistic infections like tuberculosis and increase CD4 counts." (PMID 37723415, 2023). "A systematic review showed that demographic factors such as age, sex, marital status, and employment status were important factors for loss to follow-up in addition to clinical factors such as low CD4 cell count, tuberculosis, and opportunistic infections." (PMID 38288430, 2023). "We also found strong associations of mortality with nadir CD4 as previously reported from a large US cohort, recent HIV diagnosis, and previous and especially recent/current tuberculosis co‐infection." (PMID 37339333, 2023). "We reported an HIV-infected man with low CD4 count and multidrug-resistant tuberculosis developed a generalised lichenoid eruption that progressively worsened and depigmented after initiating tuberculosis treatment." (PMID 37216149, 2023). "Multifunctional CD4+T cells have been reported frequently among tuberculosis patients, individuals from endemic tuberculosis areas, and vaccinated infants." (PMID 37415827, 2023). "Significant risk factors for tuberculosis incidence in HIV patients were being underweight, having anemia, being male, having low CD4 counts, being in advanced WHO clinical stages, being bedridden/ambulatory, lacking cotrimoxazole, and lacking IPT." (PMID 37723415, 2023). "As with other immunosuppressants, there is an increase in the risk of opportunistic infections in PWH, particularly those with low CD4 counts; special attention should be given towards tuberculosis." (PMID 36851791, 2023). "Our data thus propose OX40 as a marker of recently activated CD4 T cells at the infection site and a potential target for immunotherapy in tuberculosis." (PMID 38110410, 2023). "The risk of dying from pneumonia and tuberculosis was independently associated with age, HIV-seropositivity and, in PLWH, higher VL and lower CD4+ counts." (PMID 37153012, 2023). "The prevailing model of protective immunity to tuberculosis is that CD4 T cells produce the cytokine IFN-γ to activate bactericidal mechanisms in infected macrophages." (PMID 35877763, 2022).
tuberculosis (continued). "At present, most of these adjuvants are involved in Th1-type reaction derived from CD4+ T cells, which plays an important role in anti-tuberculosis immunity." (PMID 36504851, 2022). "In contrast, two papers reported the presence of a subset of Foxp3+ cells within KLRG1+CD4+ cells isolated from tuberculosis patient PBMC and ovarian cancer tumor microenvironment." (PMID 35572605, 2022). "The elevated IFN-γ levels observed here both in M. tuberculosis-infected CD84-deficient mice (at 80 days postinfection) and in CD84− CD4+ T cells from TB patients may be related to the increased levels of Th1 or CD8+ T cell differentiation detected." (PMID 35196822, 2022). "For participants with a CD4 count of 200 cells per μL or less, the prevalence of tuberculosis was 13·7% (11·1–16·7) and among those with a CD4 count of more than 200 cells per μL it was 4·9% (3·6–6·6)." (PMID 34800394, 2022). "It is generally accepted that CD4+ T-lymphocytes are an essential component of protective immunity against tuberculosis." (PMID 36160177, 2022). "Tuberculosis and Talaromyces marneffei (TM) infection should be considered in patients with CD4 cell counts < 50 cells/mm3." (PMID 35042469, 2022). "When HIV positive, testing included cryptococcal antigen, CD4 count, and urine lateral flow lipoarabinomannan assay for tuberculosis." (PMID 36411415, 2022). "The differences in some opportunistic infections, such as tuberculosis, talaromycosis, and septicemia, between the two CD4 count groups were statistically significant." (PMID 35042469, 2022). "The low CD4 count, female gender, and concomitant infection with Penicillium marneffei, Hepatitis C virus, or Tuberculosis were independent correlates of anemia." (PMID 36474196, 2022). "Antiretroviral drugs, baseline CD4 count or viral load, and tuberculosis (TB) screening were available in less than 50% of the health centers." (PMID 36584222, 2022). "One patient in group III developed tuberculosis in her chemotherapy period with a CD4 count of 93 cells/μl and an undetected viral load level." (PMID 36151562, 2022). "In populations with high prevalence of TB-IRIS risk factors (low CD4 counts and short interval between antituberculosis treatment and ART initiation), the incidence of TB-IRIS may exceed 50% 18,19." (PMID 35175970, 2022). "Compared to patients with CD4 counts ≥ 50 cells/mm3, those with CD4 counts < 50 cells/mm3 were 0.43 (95% CI: 0.22, 0.84; p value = 0.01) times less likely to be infected with tuberculosis." (PMID 35042469, 2022). "The hazard of tuberculosis was 3.14 times higher among participants with CD4 count <200 compared to their counterparts." (PMID 35921384, 2022). "For instance, short lived, highly apoptotic, terminally differentiated and effector cytokine secreting KLRG1+CD4+ T cell populations are significantly upregulated in tuberculosis patients." (PMID 35572605, 2022). "Control of tuberculosis depends on the rapid expression of protective CD4+ T-cell responses in the Mycobacterium tuberculosis (Mtb)-infected lungs." (PMID 35935958, 2022). "Advanced clinical stage, low CD4+ cell count, and previous episodes of an opportunistic infection other than tuberculosis were found to be independent predictors of mortality." (PMID 36315573, 2022). "The risk of tuberculosis and TM infection was high in FUO-HIV patients with CD4 cell counts < 50 cells/mm3." (PMID 35042469, 2022). "The 76 Histoplasma antigen–positive participants had significantly lower (p = 0.03) CD4 counts; 9 (11.8%) were also co-infected with tuberculosis." (PMID 36286009, 2022). "In some patients with active tuberculosis, CD4+ percentage and absolute value reduction in the peripheral blood was found, which was related with the severity of infection." (PMID 35216349, 2022). "It increases their work load because there is also a lot of documentation, counseling and follow-up of clients, viral load, CD4, tuberculosis screening." (PMID 36206224, 2022).
tuberculosis (continued). "Screening for tuberculosis and TM infection should be recommended for patients with CD4 counts < 50 cells/mm3." (PMID 35042469, 2022). "The difference in the incidence of tuberculosis was statistically significant between the two of CD4 cell count groups." (PMID 35042469, 2022). "A previous study by our group demonstrated that Advax-CpG formulated with a tuberculosis vaccine enhanced CD4+ IFN-γ and IL-17A responses after challenge, but the CpG component was dispensable for protective efficacy." (PMID 36411332, 2022). "We investigated changes of activation and maturation markers on MTB-specific CD4+ T-cells after anti-tuberculosis treatment initiation in relation to HIV status and the severity of lung impairment." (PMID 36145465, 2022). "It revealed that Uyghurs, females, depressed CD4 count, decreased BMI, a previous history of tuberculosis (TB), and oral candidiasis were independently correlated risk factors for anemia." (PMID 36474196, 2022). "In support of these findings, it has been demonstrated that mucosal BCG vaccination, as well as the CAF01-adjuvanted fusion protein Ag85B-ESAT6, induces an antigen specific KLRG1- CD4+ T cell population, which confers better protection against tuberculosis." (PMID 35572605, 2022). "For example, an HLA-DR+ NK cell subset was found to be expanded in the peripheral blood of patients with primary tuberculosis and to mediate cytokine production by CD4+ T cells." (PMID 36618376, 2022). "In active tuberculosis, for example, HLA-DR marks a CD4+ T cell population that contains recently divided antigen-specific effector T cells." (PMID 35812429, 2022). "Since the association between HLA class II and tuberculosis infection has been reported in several population groups, a detailed study on the CD4+ T cell response to major tuberculosis antigens is needed." (PMID 35967347, 2022). "Tuberculosis was the predominant comorbidity (15.7%, n = 47) and majority (53.0%, n = 159) had a CD4 count of < 500 cells/ml." (PMID 34527139, 2021). "The protective efficacy of anti-tuberculosis immune response is largely dependent on Th1-polarised CD4+ T-cells and CD8+ CTLs." (PMID 34835204, 2021). "tuberculosis-specific response; however to our knowledge this is the first report of a STINGa-dependent modulation of CD4 T cell polarization in a cancer immunotherapy context." (PMID 34276686, 2021). "In March 2021, World Health Organization recommended that antiretroviral therapy (ART) should be started within two weeks of tuberculosis treatment start, at any CD4 count." (PMID 34289243, 2021). "However, clinical and experimental findings reported that CD4+IFN-γ+ cells against M. tuberculosis antigens are directly or indirectly implicated in TB pathogenesis." (PMID 34359902, 2021). "Previous studies have verified some cytokine secretion profiles from CD4+ T cells in patients with tuberculosis, such as IFN-γ+, TNF-α, IL-2 and CD27." (PMID 34176483, 2021). "It is a major immunodominant antigen that is considered to have potential as a vaccine against tuberculosis, and can elicit proliferation of both CD4+ and CD8+ T cells and IFN-γ secretion in healthy people with LTBI44." (PMID 34267288, 2021). "Different studies identified that advanced WHO clinical stages while initiating ART, co-morbid conditions, low hemoglobin level, IPT use, and low CD4 count contribute to the occurrence of opportunistic infections including tuberculosis after initiation of ART." (PMID 33724992, 2021). "The patients infected with tuberculosis and showing a small number of CD4 can show atypical chest imaging findings, and even normal chest imaging findings." (PMID 34277657, 2021). "These immune dysfunctions were consistent with PD1/Tim3 up-regulation on CD4+CD161+ T cells in active tuberculosis patients, and the blockade of PD1/Tim3 on this subset cells enhanced the inhibition of intracellular mycobacteria survival." (PMID 33732233, 2021).
tuberculosis (continued). "In a head-to-head comparison of the k91 DICE clusters against the BTMs, the k91 DICE clusters were determined to be much higher quality than the BTMs when attempting to capture the “Burel” 74-gene CD4 T-cell tuberculosis signature." (PMID 34613979, 2021). "We avoided the use of antigens such as ESAT6 that directly stimulate CD4 + T cells of tuberculosis patients in a MHC class II restricted manner." (PMID 34237073, 2021). "This is since being stages III and IV will have low CD4 cell count and ultimately be unable to defend against infections including tuberculosis." (PMID 33632342, 2021). "Patients including, women, individuals aged > 25 years, those with low CD4 count, individuals with high body mass index, individuals co-infected with tuberculosis, and those who had access to free cotrimoxazole treatment were more likely to remain in care." (PMID 33743815, 2021). "Tuberculosis can occur during any stage of Human Immunodeficiency virus 1 (HIV) -infection including times when CD4+ T cell numbers have reconstituted and viral replication suppressed." (PMID 33995365, 2021). "An important diagnostic element of this package is to test sputum for tuberculosis (TB) using the Xpert MTB/RIF assay for all symptomatic adults, and to test urine using lateral-flow lipoarabinomannan (LF-LAM) in adults with CD4 counts less than 100 cells/μL." (PMID 34662866, 2021). "CD4 count at baseline of ART initiation was a significant pooled factor for developing tuberculosis among six articles." (PMID 33632342, 2021). "The resulting model (p = 0.003, pseudo R2 = 0.23) incorporated weight, tuberculosis, lower nadir CD4 T-cell count and rs4947324*T." (PMID 31936167, 2020). "Previous studies have demonstrated that the delicate balance of a P. chabaudi-infected animal's life or death is regulated by CD4 T cells, as is the case in other persistent infections such as tuberculosis and toxoplasmosis." (PMID 32634740, 2020). "Recently, it was shown in a mouse model and in patients with tuberculosis that PD-1 blockade mounted rampant CD4+ T helper type 1 (Th1) responses driving lethal disseminated tuberculosis." (PMID 33511078, 2020). "Hazards were significantly higher for elderly patients at least 74 years of age (HR 6.48; 95% CI 2.99–14.07) and younger adults aged 18 to 38 years (HR 1.53; 95% CI 1.15–2.04), adjusting for CD4 count, gender, adherence, and diagnosis of tuberculosis." (PMID 32481319, 2020). "Eligibility criteria were first increased to CD4 <350 cells/μl for pregnant women and people with active tuberculosis (TB) disease, then later for all HIV-infected adults." (PMID 33232331, 2020). "Host defense against tuberculosis is mainly mediated by the cell-mediated immune response which involves the various subsets of lymphocytes, including the CD4 + and CD8 + T cells, and their depletion triggers host vulnerability to TB." (PMID 32033581, 2020). "Baseline CD4 count, nutritional status, and exposure to tuberculosis treatment were the independent predictors for the development of OIs." (PMID 32126978, 2020). "Separate Cox proportional hazard models were built for each outcome and eligibility period, adjusted for tuberculosis, pregnancy, CD4 count and age." (PMID 32589367, 2020). "Extensive studies reported significant improvements in mean CD4+ T lymphocyte counts after patients received anti-tuberculosis treatments." (PMID 32033581, 2020). "Prolonged exposure to tuberculosis antigens does lead to an increased expression of PD-1 on CD4 and CD8 T cells, and blocking PD-1 or PD-L1 with an antibody increases CD4 and CD8 T cell activity." (PMID 32858811, 2020). "A modified version of the vaccine containing Rv2660 protein (H56), ESAT-6-Ag85B, and CAF01 activated CD4+ cells protected mice in a tuberculosis challenge performed one-year post-vaccination." (PMID 33066594, 2020).